KRAS (KRas proto-oncogene, GTPase)
Diseases named in the same sentence as KRAS in open-access papers (continued):
Sharing a sentence is not in itself a finding about the gene and the disease.
rectal cancer (185 papers, 1991 to 2026). A primary or metastatic malignant neoplasm that affects the rectum. "Currently, the application of radiomics in predicting KRAS mutations in rectal cancer has been explored in several studies." (PMID 40653800, 2025). "The ultrasound radiomics model, utilizing both intratumoral and peritumoral features, demonstrates effective diagnostic capability in predicting KRAS status in rectal cancer patients." (PMID 40653800, 2025). "Previous studies have demonstrated that radiomics features derived from CT, MRI, and PET/CT images effectively predict KRAS mutations in rectal cancer." (PMID 40653800, 2025). "In conclusion, the ultrasound radiomics model, utilizing both intratumoral and peritumoral features, demonstrates effective diagnostic capability in predicting KRAS status in rectal cancer patients." (PMID 40653800, 2025). "New therapies targeting the KRAS mutation have been investigated to optimize treatment for this subgroup of rectal cancer." (PMID 40653800, 2025). "We aim to develop a radiomics model utilizing intratumoral and peritumoral ultrasound images for predicting KRAS mutation status in rectal cancer." (PMID 40653800, 2025). "Early detection of KRAS mutation status in rectal cancer is crucial for selecting appropriate clinical targeted therapies." (PMID 40653800, 2025). "Conversely, KRAS p.Gly12Val and p.Gly13Asp mutations were associated with decreased likelihood of rectal cancer and left-sided CRC, respectively." (PMID 39857025, 2025). "Conversely, KRAS p.Gly12Val and p.Gly13Asp mutations were associated with decreased likelihood of rectal cancer (53% lower) and left-sided tumors (56% lower), respectively." (PMID 39857025, 2025). "Rectal cancers have higher rates of locoregional relapse, a preference for lung metastases and a lower frequency of KRAS and BRAF mutations." (PMID 39827162, 2025). "Radiomics research in rectal cancer has been reported in tumour stage classification, lymph node metastasis, liver metastasis, KRAS mutation and MSS status." (PMID 40293520, 2025). "Our study discovered that the peritumoral tissue of rectal cancer plays a significant role in predicting KRAS mutations." (PMID 40653800, 2025). "KRAS p.Gly12Val and p.Gly13Asp mutations were associated with decreased likelihood of rectal cancer and left-sided tumors, respectively." (PMID 39857025, 2025). "For example, KRAS mutation predicts poor prognosis in rectal cancer patients undergoing neoadjuvant chemoradiotherapy." (PMID 38706597, 2024). "Our previous study showed that the diameter of the superior rectal vein was significantly increased in patients with rectal cancer carrying the KRAS mutation." (PMID 38726026, 2024). "Current research on radiomics in rectal cancer mainly focuses on predicting aspects such as complete remission after neoadjuvant therapy for advanced rectal cancer, lymph node metastasis, KRAS/NRAS gene mutations, and microsatellite instability (MSI)." (PMID 37941552, 2023). "A previous study found that morphological features (elongation and flatness) were closely associated with KRAS mutations in rectal cancer." (PMID 37311935, 2023). "Prognostic associations of variant KRAS in our study were limited to YO left-sided and rectal cancers." (PMID 38032636, 2023). "KRAS mutation is an independent prognostic factor and is known to be resistant to chemotherapy in rectal cancer." (PMID 36826155, 2023). "The impact of KRAS mutations on rectal cancer is not yet fully understood, and there is limited data on mutations in exons 3 and 4 due to their low occurrence rate." (PMID 37628934, 2023). "Fifty-four patients with KRAS-mutated T3/4 and/or N1/2M0 locally advanced rectal cancers were included and treated with neoadjuvant treatment with radiotherapy (45 Gy in 25 fractions over 5 weeks) and capecitabine 825 mg/m2 twice daily plus sorafenib 400 mg/d." (PMID 36836752, 2023).
rectal cancer (continued). "A population-based analysis indicated that KRAS mutation had prognostic value for poor cancer-specific survival in rectal cancer (HR 1.23, p < 0.05)." (PMID 38087207, 2023). "As shown in our results, we detected the same KRAS mutation in both tissue (either from the primary or metastatic site) and plasma ctDNA of the P4, P5, and P6 metastatic rectal cancer patients." (PMID 37511664, 2023). "Histological findings and KRAS mutation analysis suggested implantation of sigmoid colon cancer to the post-endoscopic submucosal dissection site of intramucosal rectal cancer." (PMID 36514801, 2022). "The results showed that age, preoperative serum CEA, CA19-9, and CA125, differentiation status, T stage, N stage, KRAS mutation, and postoperative chemotherapy were independent prognostic factors for the prognosis of rectal cancer." (PMID 35784233, 2022). "Another study found that rectal cancers with different KRAS mutation statuses had distinctive diffusion/perfusion characteristics." (PMID 36276105, 2022). "As a proof-of-concept, the influence of KRAS mutation-mediated resistance to EGFR-targeted therapy using cetuximab was tested in rectal cancer organoids." (PMID 33816288, 2021). "Two studies evaluated the association between T2w MR radiomics and KRAS mutational status in rectal cancer." (PMID 34208595, 2021). "Here we have evaluated spatio-temporal functional and molecular dynamics of five PDO models established after hepatic re-resections and neoadjuvant combination chemotherapies in a patient with microsatellite stable and KRAS mutated metastatic rectal cancer." (PMID 34496878, 2021). "Here, we employed a multidisciplinary approach to analyze spatio-temporal pharmacogenomic heterogeneity in a patient with recurrent, KRAS mutated liver metastases from rectal cancer." (PMID 34496878, 2021). "Here, we report a longitudinal, observational co-clinical study of standard combination chemotherapies in a patient with recurrent, KRAS mutated liver metastases from rectal cancer." (PMID 34496878, 2021). "A 64 year old man was diagnosed with KRAS mutated (codon G13D), microsatellite stable rectal cancer disseminated to the liver (T3N0M1)." (PMID 34496878, 2021). "KRAS mutation status was analyzed from 47 patients with locally advanced rectal cancer, which were enrolled in the CAO/ARO/AIO-94 or CAO/ARO/AIO-04 trial." (PMID 33002027, 2020). "KRAS mutation status is significant concordant between areas of the primary tumor and the corresponding metastasis in patients with advanced rectal cancer treated preoperatively with CRT." (PMID 33002027, 2020). "The investigated cohort in this study harbored a KRAS mutation frequency of 46% which is in line with current data for colon and rectal cancer." (PMID 33002027, 2020). "KRAS mutations occur early in CRC development and the role of KRAS mutations in response to NACRT in rectal cancer is conflicting." (PMID 32640573, 2020). "In agreement with our study, a recent investigation showed that 43% of rectal cancer patients were KRAS mutation positive for paired cfDNA from those with KRAS mutations." (PMID 32520974, 2020).
rectal cancer (continued). "In the present study, rectal cancer with KRAS mutation had higher Entropy values compared to the KRASwt group (p < 0.0001)." (PMID 31727020, 2019). "In other words, rectal cancer with KRAS mutation had higher intrinsic heterogeneity than KRAS wild-type cancers did; this intrinsic heterogeneity in KARS mutation should be addressed more in detail by further research." (PMID 31727020, 2019). "The mutation rate of KRAS gene in female (53.7%) is significantly higher than that of male (30.3%) (p = 0.012) analyzed by Chi-square test in rectal cancer." (PMID 30416987, 2018). "Using the sensitive technology of NGS, comparing biopsy with resection, we describe for the first time substantial loss and gain of EGFR pathway mutations (mainly KRAS) in locally advanced rectal cancer undergoing pre-operative CRT." (PMID 28859058, 2017). "Molecular analysis using pyrosequencing showed the same KRAS mutation (c.38G > A) in both the rectal cancer (tested on the biopsy) and the lung tumour, supporting that the lung and liver tumours were metastases of the rectal cancer." (PMID 28347348, 2017). "KRAS oncogene mutations (MUTKRAS) drive resistance to EGFR inhibition by providing alternative signaling as demonstrated in colo-rectal cancer." (PMID 26799287, 2017). "Our results indicate that the KRAS mutation status at the primary tumor site of rectal cancer is homogenous." (PMID 27064574, 2016). "KRAS mutation status analyses were performed in 199 tumor samples from 47 patients with rectal cancer." (PMID 27064574, 2016). "In advanced stage CRCs, rectal cancers showed a higher frequency of KRAS mutation (p = 0.03); meanwhile, BRAF mutation was related to female sex (p = 0.04) and less lymph node invasion (p = 0.05)." (PMID 25734426, 2015). "In a study of 96 locally advanced rectal cancer patients undergoing neoadjuvant chemoradiation therapy, 38% had KRAS mutations." (PMID 24265711, 2013). "KRAS mutations, are reported in 19 to 48% of patients with rectal cancer, whereas BRAF mutations are found in 0 to 12% of RC patients." (PMID 23617638, 2013). "Shortly thereafter, Gaedcke and colleagues observed a KRAS mutation frequency of 48% (n = 45) in pretherapeutic biopsies of 94 patients with locally advanced rectal cancers." (PMID 22382702, 2012). "KRAS mutation status appears to influence response to therapy in patients with locally advanced primary rectal cancer." (PMID 23202889, 2012). "Luna-Perez and colleagues correlated the response of 37 rectal cancers to preoperative chemoradiotherapy with KRAS mutation status." (PMID 22382702, 2012). "In contrast, Zauber and colleagues screened pretherapeutic biopsies from 53 patients with stage I–III rectal cancers and detected KRAS mutations in 18 patients (34%)." (PMID 22382702, 2012). "In conclusion, our experience from predictive testing for KRAS mutations reveal a high mutation frequency (67%) in rectal cancers from females and thus implicates that this subset is the least likely to respond to anti-EGFR therapies." (PMID 19832985, 2009). "Therefore, early detection of KRAS mutation status in rectal cancer is conducive to the choice of clinical therapy." (PMID 40653800, 2025). "However, approximately 40% of rectal cancer patients possess KRAS mutations, which activate the RAS membrane receptor tyrosine protein kinase signaling pathway, disrupt upstream signal regulation, and promote tumor cell proliferation." (PMID 40653800, 2025). "KRAS mutation is independently associated with a lower pCR rate in locally advanced rectal cancer." (PMID 41463244, 2025). "Indeed, the highest percentage of KRAS‐mutated samples were from pancreatic, colon and rectal cancers." (PMID 40013338, 2025).
rectal cancer (continued). "Pre-clinical investigations have shown that KRAS mutations could cause not only a more aggressive tumor phenotype, but also resistance to radiotherapy in rectal cancer." (PMID 36900260, 2023). "Although whether the feasibility and safety of intratumoral injection of OBP-702 in CRC patients remains to be elucidated, rectal cancers with KRAS/BRAF mutations may be potent candidate for treating with OBP-301 and OBP-702." (PMID 37972012, 2023). "Whether the response of rectal cancer to nCRT is associated with the somatic mutations of KRAS or APC and infiltration of activated CD4+ T cells, NK cells, dendritic cells, or M2 macrophages should be verified in future investigations." (PMID 36621808, 2023). "The association analysis of the clinical variables of the CRC patients with the KRAS gene variants showed that being a carrier of the CC and TC genotypes of the rs8720 variant was linked with rectal cancer, an advanced age over 50 years, progression, and moderately differentiated histology." (PMID 37566020, 2023). "Mutated KRAS may indicate an invasive nature and predict prognosis in locally advanced rectal cancer (LARC)." (PMID 38087207, 2023). "After two years, they published another study showing that mutations in different KRAS codons may have different effects on rectal cancer resistance to CRT." (PMID 35682714, 2022). "The results showed that age, CEA, CA19-9, CA125, preoperative chemotherapy, macropathology type, tumor size, differentiation status, T stage, N stage, lymphovascular invasion, KRAS mutation, and postoperative chemotherapy were associated with the prognosis of patients with rectal cancer." (PMID 35784233, 2022). "We therefore investigated whether deep learning–based segmentation is feasible in predicting KRAS/NRAS/BRAF mutations of rectal cancer using MR-based radiomics." (PMID 34395262, 2021). "The unique set of human rectal cancer specimens that we have analyzed provides an anatomically homogenous population in which to study both cancer cell‐intrinsic and stromal changes driven by KRAS mutations." (PMID 33817986, 2021). "Therefore, we recommend cranial imaging in patients with symptoms or if risk factors are present (KRAS mutation, pulmonary metastases, rectal cancer, or positive CEA level)." (PMID 33669974, 2021). "Regarding rectal cancer solely, this study is to our knowledge one of the largest cohort for the specific evaluation of intra- and intertumoral KRAS mutation status heterogeneity in patients with locally advanced rectal cancer who were treated preoperatively with CRT within a clinical study setting." (PMID 33002027, 2020). "T2-weighted images could be used to predict KRAS mutation status preoperatively in patients with rectal cancer." (PMID 32858990, 2020). "KRAS mutation status in patients with metastasized rectal cancer." (PMID 33002027, 2020). "However, several reports suggested a difference in the expression pattern of genes in colon and rectal tumors along with the significant differences in the mutation level of APC and KRAS mutation between colon and rectal cancer." (PMID 33457124, 2020). "Approximately 30–40% CRCs have KRAS mutation, while rectal cancer accounts for 30–35% among CRC." (PMID 31727020, 2019). "The lower ADC value observed in rectal cancers with KRAS mutation may suggest an unfavorable tumor profile." (PMID 31727020, 2019). "Although rectal cancers with KRAS mutation were mainly located in the middle-low part of rectum and had an extent of over 3/4 bowel circumference, there was no statistical difference between the KRASmt group and the KRASwt group (p = 0.095 and 0.872, respectively)." (PMID 31727020, 2019). "It has been shown that the expression of cyclooxygenase-2, vascular endothelial growth factor, and Raf kinase inhibitor protein and the mutational status of KRAS represent valuable molecular markers that can be used for predicting treatment outcomes in rectal cancer patients." (PMID 30572939, 2018).
rectal cancer (continued). "Thus, we aimed to evaluate the clinical association between KRAS oncogene status and treatment outcome in locally advanced rectal cancer." (PMID 26252300, 2015). "Whether the KRAS mutation status also influences the response of rectal cancers to multimodal treatment concepts that include EGFR inhibitors remains elusive, particularly as the clinical relevance of these combinations remains to be determined." (PMID 22382702, 2012). "KRAS exon 2 mutations were detected in 13 (35.1%) of the 37 rectal carcinomas of the test series." (PMID 20979647, 2010). "The effect seems to be limited to females with rectal cancer, 67% of whom harbored KRAS mutations." (PMID 19832985, 2009). "Although previous studies utilized expanded peritumoral regions (10, 20, and 30 pixels) combined with radiomics and deep learning features to predict KRAS mutation status in rectal cancer via ERUS imaging, the impact of a fixed physical peritumoral width remains unclear." (PMID 40653800, 2025). "Therefore, lower ADC values in the mutated group may indirectly confirm the association between KRAS mutation and prognosis in rectal cancer." (PMID 39416464, 2024). "In addition, it has been reported that KRAS mutation may be related to distant recurrence in rectal cancer." (PMID 38087207, 2023). "In a former study our results demonstrated the reliable detection of KRAS mutation status for therapeutic decisions in pre-therapeutic biopsies as well as in post-therapeutic residual tumor tissue in patients with locally advanced rectal cancer who were treated preoperatively with chemoradiotherapy." (PMID 33002027, 2020). "In this study, we were able to prove that KRAS mutation status is statistically significant homogeneous between the primary tumor and the corresponding metastatic tissue in patients with locally advanced rectal cancer by applying a sensitive pyrosequencing method." (PMID 33002027, 2020). "In a previously published work we have shown the valid assessment of KRAS mutation status for therapeutic decisions in pre-therapeutic (treatment naïve) biopsies as well as in post-therapeutic (after preoperative CRT) residual tumor tissue in patients with locally advanced rectal cancer." (PMID 33002027, 2020). "However, the role of KRAS or NRAS mutations in localized rectal cancer is uncertain." (PMID 27655166, 2016). "combined MRI radiomics (e.g. Imc1, Coarseness) with KRAS/CEA for rectal cancer liver metastasis prediction (combined AUC 0.842; KRAS odds ratio 8.296), underscoring mutations' independence for model prediction." (PMID 41583907, 2026). "Future research will delve deeper into the predictive value of shear wave features for the KRAS in rectal cancer, aiming to more comprehensively evaluate the efficacy of ultrasound in detecting KRAS mutations in rectal cancer." (PMID 40653800, 2025). "The ultrasound radiomics model, incorporating both intratumoral and peritumoral features, effectively predicts KRAS status in rectal cancer patients, potentially guiding clinical targeted therapy selection." (PMID 40653800, 2025). "This study confirms the non-invasive preoperative evaluation of the KRAS gene expression in rectal cancer patients via radiological indicators, assisting in the development of individualized treatment strategies at the imaging level." (PMID 40421293, 2025). "Risk factors for BM include lung metastasis at diagnosis, rectal cancer, and mutations in RAS and KRAS genes." (PMID 39311160, 2024). "Next, we tested the combination of ERK and CDK8/19 inhibition in three KRAS-mutant, patient-derived tumoroid models of rectal cancer." (PMID 38822082, 2024).